ALB (albumin)
Diseases named in the same sentence as ALB in open-access papers (continued):
Sharing a sentence is not in itself a finding about the gene and the disease.
Hypertension (continued). "Lastly, using a MR approach, we provided evidence that higher UNa/UK is causally related with higher blood pressure, and we highlighted a causal feedback loop between albumin and hypertension and between albumin and T2D." (PMID 32008434, 2020). "This study extends previous investigations by showing associations between the level of urinary albumin excretion and hypertension as well as markers of arterial stiffness and subclinical atherosclerosis in young and mostly healthy individuals." (PMID 32758145, 2020). "Overall, the most common AEs of any grade were hand‐foot syndrome (n = 23, 56.1%), general fatigue (n = 24, 58.5%), loss of appetite (n = 28, 68.3%), hypertension (n = 28, 68.3%), and increased urinary albumin (n = 23, 56.1%)." (PMID 32055698, 2020). "A multivariate logistic regression analysis showed that hyperuricemia, hypertension, and serum albumin level were independent risk factors for the development of CKD in males." (PMID 31818273, 2019). "Logistic regression showed that hyperuricemia, hypertension, high total cholesterol level, and low albumin were independent risk factors for CKD development in male patients." (PMID 31818273, 2019). "The TCA was significantly associated with the age, axial length, sex, albumin index, the stage of DR, and hypertension." (PMID 31700083, 2019). "Hyperuricemia was a strong independent risk factor for CKD in both genders, while hypertension and low serum albumin were risk factors for CKD only in males." (PMID 31818273, 2019). "Low albumin was associated with increasing age, women gender, hypertension, peripheral vascular disease, prior stroke, dementia, and increased Charlson Comorbidity Index but less with ischemic heart disease." (PMID 30637771, 2019). "Rather than the type of surgery, variables including history of hypertension, preoperative albumin level, and synthetic colloid infusion were associated with the occurrence of postoperative AKI." (PMID 30142190, 2018). "For example, animal studies have shown that GLP-1 RA use is associated with natriuresis and diureses and that these agents also reduce risk factors of diabetic nephropathy, by reducing urine albumin levels and inhibiting the development of hypertension." (PMID 29460259, 2018). "A key mechanism for obesity-associated albuminuria is intraglomerular hypertension, which increases renal blood flow and fractional urinary albumin clearance." (PMID 29343817, 2018). "According to the results of the current work, high total antioxidant capacity of the diet was associated with the lower prevalence of hypertension, lower hematocrit and higher serum albumin concentrations in male candidate for CABG." (PMID 30540842, 2018). "In summary, our study found that the SNP in rs1045642 was associated with CR in patients with hypertension or albumin ≥35 and was related to all-cause mortality." (PMID 28358842, 2017). "If patients did not have hypoproteinaemia or had hypertension, the SNP in rs1045642 was associated with CR (CC vs. TT: albumin ≥35, P = 0.042; hypertension, P = 0.045; C vs. T: albumin ≥35, P = 0.033; hypertension, P = 0.040)." (PMID 28358842, 2017). "For rs1045642, in patients with hypertension or a value of albumin greater than 35, patients with the CC genotype had a higher risk of CR than those with the TT genotype (albumin≥35, P = 0.042; hypertension P = 0.045)." (PMID 28358842, 2017). "In univariate analysis, age (p < .0001), race (p = 0.01), albumin (p = 0.0005), congestive heart failure (p = 0.004), hypertension (p = 0.003), and cancer (p = 0.03) were associated with an increase in mortality." (PMID 28764654, 2017). "Urinary albumin levels and hypertension (HTN) are independently associated with an increased risk of all-cause mortality." (PMID 28472229, 2017). "The majority of patients also had other well-defined risk factors (e.g., COPD, hypertension, low albumin, and poor tissue quality)." (PMID 27026831, 2016).
Hypertension (continued). "The increase in factors, including body weight, and the blood levels of glucose, triglycerides, and albumin elevated the risk of hypertension in subjects as well." (PMID 29367559, 2016). "The findings indicated that female gender and an increase in the factors of body weight and the blood levels of triglycerides, albumin, and glucose enhanced the risk of hypertension in subjects." (PMID 29367559, 2016). "It was concluded that female gender, enhanced body weight and increase in the blood levels of glucose, triglycerides, and albumin increased the risk of hypertension in subjects." (PMID 29367559, 2016). "It was concluded that female gender, an increase in body weight, and an increase in the blood levels of glucose, triglycerides, and albumin enhanced the risk of high blood pressure in the Malaysian elderly." (PMID 29367559, 2016). "The close association between urinary albumin and the development of hypertension was further supported by the finding that UACR taken as a continuous variable was a significant and independent predictor of future hypertension." (PMID 25674745, 2015). "The risk of developing hypertension increases even with levels of urinary albumin near the threshold defined for microalbuminuria." (PMID 25674745, 2015). "The present study demonstrated that any level of increased urinary albumin was closely associated with the risk for developing hypertension in the Japanese general population." (PMID 25674745, 2015). "Other factors that were significantly associated with ADPKD included hypertension, tobacco use, higher mean hemoglobin, higher mean serum albumin, higher mean total cholesterol, higher mean low density lipoprotein (LDL) and BMI." (PMID 24571546, 2014). "Aside from pre-pregnancy adiposity and raised blood pressure, two additional risk factors associated with poor metabolic health, elevated albumin:creatinine and the γ -glutamyl transferase, increased the risk for hypertension during pregnancy among the cohort." (PMID 23410045, 2013). "Older age, male sex, family history of hypertension, greater baseline body mass index, weight gain, and greater albumin excretion rate were independently associated with increased risk of hypertension." (PMID 24165454, 2013). "In a Japanese study on elderly people, health behavior and social role were risk factors for all-cause mortality along with age, low serum albumin, high blood pressure and ECG abnormalities, among a total of 30 personal characteristics." (PMID 22824187, 2012). "The PAR, which can be easily calculated using PDW and serum albumin from routine laboratory tests, could serve as a valuable marker for risk stratification in clinical hypertension management." (PMID 40593009, 2025). "The increased risk of hypertension among those with hyperglycemia may be a consequence of kidney damage, assessed with elevated levels of albumin excretion." (PMID 41009768, 2025). "The multivariate logistic regression analysis showed that BMI, high blood pressure, chronic bronchitis, peptic ulcer, operation way, anastomotic location, and postoperative albumin were independent risk factors for postoperative anastomotic leakage of esophageal cancer (p < 0.05)." (PMID 40956011, 2025). "Previous studies have shown that normotensive children of hypertensive parents have increased urinary albumin excretion, which may further support the premise that microalbuminuria is an early finding in individuals with a predisposition to hypertension." (PMID 38586159, 2024). "Overweight, hypertension, higher HbA1c, high HbA1c, and dyslipidemia were significantly positively associated with serum albumin levels, while age, normal-low weight, daily drinker, and smoker were significantly inversely associated with serum albumin levels." (PMID 38802949, 2024). "In fact, there may be intricate and intrinsic links between different risk factors, such as serum albumin level, infection, and hypertension, which could contribute to the development of AKI." (PMID 39759881, 2024).
Hypertension (continued). "There may be unusually large individual differences in serum albumin concentration levels and dynamics over time, and therefore dynamic trajectories of serum albumin concentrations may more accurately predict the risk of hypertension." (PMID 38779492, 2024). "The analysis involved examining basic characteristics (age, sex), the concomitant diseases (hypertension, infections), NS disease characteristics (steroid susceptibility classification, pathologic classification), laboratory test (e.g., serum albumin), and the use of nephrotoxic drugs." (PMID 39759881, 2024). "Association between cumulative average serum albumin during 2009–2016 and risk of hypertension." (PMID 38779492, 2024). "In addition to higher serum urea and lower serum albumin levels being significantly associated with hypertension in children with nephrotic syndrome, increased BMI was found to be associated with hypertension in such children." (PMID 39396026, 2024). "High serum albumin levels reduced the risk of hypertension with a low stable trajectory as a control, moderate decrease trajectory (OR, 1.01, 95% CI, 0.83–1.24), moderate increase trajectory (OR, 0.93, 95% CI, 0.76–1.14), and high stable trajectory (OR, 0.84, 95% CI, 0.65–1.09) (P = 0.058)." (PMID 38779492, 2024). "Results from multiple studies found that high eGCSS was associated with low renin levels and high albumin-creatinine ratio in hypertension, correlated with high salt intake in a similar population from Zambia, and was associated with hypertension despite use of antihypertensive medication." (PMID 38524849, 2024). "Association between serum albumin change trajectory and risk of hypertension." (PMID 38779492, 2024). "Specifically, the selective reporting of studies with statistically significant associations between stroke and hypertension, female sex, low albumin levels, and renal insufficiency may have led to an overestimation of these effects." (PMID 37848510, 2023). "The GOA selected 12 parameters, namely age; gender; hypertension; and hemoglobin, iron, ferritin, sodium, potassium, calcium, creatinine, alkaline phosphatase, and triglyceride levels, which were significantly associated with the low serum albumin." (PMID 37095523, 2023). "Similarly, the risk of hypertension increased with the presence of increased urinary albumin excretion, ischemic heart disease, stroke, peripheral artery disease, heart failure, chronic kidney disease and atrial fibrillation." (PMID 38173815, 2023). "Age, gender, hypertension, hemoglobin, iron, ferritin, sodium, potassium, calcium, creatinine, alkaline phosphatase, and triglyceride levels were significantly associated with low serum albumin." (PMID 37095523, 2023). "Furthermore, we found effect modification by hypertension (p = 0.019), eGFR (p = 0.020) and urinary albumin excretion (p = 0.034), consistent with an association only present in participants with hypertension or kidney dysfunction." (PMID 35887628, 2022). "Although nephrologist have found several factors such as age, gender, albumin, urinary protein and people with a background of hypertension and renal microvascular lesions, are highly associated with AKI, there is still few effective and practical method for predicting AKI in MCD patients." (PMID 35685412, 2022). "Similarly, we demonstrated that plasma GDF‐15 levels are associated with the presence of hypertension, higher preprandial plasma glucose levels, lower haemoglobin and albumin levels, and impaired renal functions." (PMID 34939349, 2022). "High levels of urinary albumin excretion are associated with an increased all-cause mortality rate in the general population and high-risk patients, such as elderly subjects and those with hypertension, DM." (PMID 35359757, 2022). "Based on the results of the network analysis and molecular docking, we found that AKT1, VEGFA, eNOS, ICAM-1, PTGS2, and ALB may also be associated with the potential effects of GZD on hypertension." (PMID 33906674, 2021).
Hypertension (continued). "The top 10 important risk factors for DFU severity were serum albumin, neutrophil percentage and hemoglobin levels in whole blood, plasma fibrinogen, hemoglobin A1c, estimated glomerular filtration rate, hypertension, serum uric acid, diabetic retinopathy, and sex." (PMID 34465375, 2021). "In a cross-sectional study consisting of 454 hospitalized Iranian candidates for coronary artery bypass graft surgery, in turn, higher DTAC was associated with a lower prevalence of hypertension, lower hematocrit, lower total cholesterol, and higher albumin and vitamin D concentrations." (PMID 34335743, 2021). "Serum albumin (HR = 0.654, 95% CI 0.521–0.820) and polymorphisms of rs2894536 (HR = 1.176, 95% CI 1.015–1.361) and rs10972486 (HR = 1.152, 95% CI 1.009–1.316) were significant predictors of hypertension development." (PMID 34050200, 2021). "Although hypertension per se can be associated to increased urinary albumin excretion, hypertension is also a frequent feature of diabetic nephropathy, therefore a clear-cut distinction between the two conditions as the primary cause for albuminuria cannot be made." (PMID 33332405, 2020). "In addition, we detect a causal feedback loop between albumin and hypertension, and our finding of a bidirectional causal association between albumin and T2D reflects the well-known nephropathy in T2D." (PMID 32008434, 2020). "In addition, according to this study, many factors (e.g., high BMI, a history of hypertension, serum magnesium, and serum albumin) are found to be associated with the increased occurrence of left ventricular hypertrophy among dialysis patients." (PMID 32337146, 2020). "The pathophysiological mechanism linked to increased albumin excretion are multifactorial and mediated by increased renal vascular resistance secondary to atherosclerosis, arteriosclerosis and hypertension, chronic inflammation, increased RAAS activity and dysfunction of other hormonal systems." (PMID 32758145, 2020). "Thus, the aim of this study was to quantify the urinary miRNAs present in exosome and microvesicles (MVs), and to assess their association with the presence of increased urinary albumin excretion in essential hypertension." (PMID 30107841, 2018). "It was shown that female, hypertension, and lower albumin levels increased the risk of CR (P<0.05)." (PMID 28358842, 2017). "The findings indicated that the female gender (Odds ratio (OR) = 1.54), an increase in body weight (OR = 1.61), and an increase in the blood levels of albumin (OR = 1.51), glucose (OR = 1.92), and triglycerides (OR = 1.27) significantly increased the risk of hypertension in subjects (p < 0.05)." (PMID 29367559, 2016). "The urinary albumin reflects endothelial dysfunction and renal vascular lesions, it is a risk factor of cardiovascular events in the general population, particularly in patients with hypertension." (PMID 27729008, 2016). "The results showed that female gender (p < 0.001), an increase in body weight (p < 0.001), and an increase in the blood levels of glucose (p < 0.001), albumin (p < 0.001), and triglycerides (p = 0.025) significantly enhanced the risk of hypertension in respondents (p < 0.01)." (PMID 29367559, 2016). "Since in our study both hypertension and low albumin levels were found to be associated with CAD, it would be tempting to assume that the low levels of albumin in CAD patients could be due to higher number of hypertensives." (PMID 27350024, 2016). "However, after adjustment for hypertension and albumin the association of butyrylcholinesterase with mortality was even more distinct." (PMID 24479557, 2014). "When multivariate logistic analysis was applied, the odds of having hypertension was associated with age (1.06; 95%CI of 1.05-1.076; p<0.001), BMI (1.13; 95%CI of 1.09-1.17; p<0.001), albumin excretion rate (1.002; 95%CI of 1.001-1.003; p<0.001) and male gender (1.35; 95%CI of 1.02-1.80; p<0.001)." (PMID 23107314, 2012).
Hypertension (continued). "Serum ALB levels have been previously associated with hypertension." (PMID 22416803, 2012). "Additionally, pregnancy-related complications such as hypertension and kidney disease may result in excessive albumin loss in pregnant women, leading to decreased albumin levels." (PMID 40520340, 2025). "For nephropathy screening associated to disorders such diabetic nephropathy, hypertension, cardiovascular diseases, and chronic kidney disease, the measurement of urinary albumin is considered as a cost-effective procedure which could minimize disease progression." (PMID 34065436, 2021). "If confirmed in further studies, they may change the views on the mechanism of albumin homeostasis and the pathomechanisms of diseases associated with albuminuria, such as nephrotic syndrome, renal failure against hypertension, diabetic nephropathy and cardiovascular diseases." (PMID 34071680, 2021). "The inverse relation of serum albumin with the risk of hypertension development was attenuated in the condition of low serum albumin level (below 4 g/dL), suggesting that other confounding factor(s) may change the effect of serum albumin level on arterial blood pressure." (PMID 34050200, 2021). "However, their decreased concentrations in interstitial fluid altogether with 1-methylhistidine, glycine, and albumin lysyl may also indicate increased oxidative stress and inflammation associated with hypertension." (PMID 33187152, 2020). "Koroshi proposes that high blood pressure may cause microalbuminuria by increasing glomerular filtration pressure and subsequent renal damage and other data have linked BP control to a reduction in urine albumin levels." (PMID 31484506, 2019). "The three most influential predictors were history of hypertension, serum albumin level, and TCV, followed by age, creatinine, admission blood glucose, platelet count, NIHSS, neutrophil-to-lymphocyte ratio, and onset-to-door time." (PMID 40852520, 2025). "Similar trends were observed in the validation set, where the TT group showed lower GCS scores, larger HV, higher WBC and glucose levels, a higher prevalence of hypertension, and notably lower serum albumin levels (36.15 vs. 39.24 mmol/L, p < 0.001)." (PMID 41267968, 2025). "Our model incorporates factors such as age, history of stroke, hypertension, triiodothyronine levels, albumin-globulin ratio, and homocysteine levels, all of which demonstrated significant associations with WMH occurrence." (PMID 41311702, 2025). "Studies from Thailand support the role of 20-HETE in Cd-induced hypertension; an association of urinary 20-HETE and urinary Cd was found in women only, while urinary 20-HETE and SBP were associated with an increased albumin excretion in men." (PMID 40278154, 2025). "This study revealed considerable intergroup differences in variables such as alcohol consumption, albumin and TG levels, BMI, hypertension, age, and glycated hemoglobin level between the OA and control groups." (PMID 40802604, 2025). "Hypertension, cardiovascular disease, elevated SBP, high fasting blood sugar, and higher urinary albumin-to-creatinine ratio (uACR) were significantly associated with rapid progression (p < 0.05)." (PMID 41027831, 2025). "The pathophysiological mechanism involves uric acid-mediated activation of the RAAS leading to vasoconstriction, while decreased serum albumin induces vasoconstriction through oxidative stress pathways, both culminating in hypertension." (PMID 39897307, 2025). "A significant relationship was found between malignancy, hypertension, low albumin, NLR, and CRP values with mortality." (PMID 40521831, 2025). "The propensity score model included age, hypertension, coronary artery disease, heart failure, cancer, albumin, blood urea nitrogen, low-density lipoprotein, triglycerides, hemoglobin, and the use of RASi, SGLT2i, beta-blockers, CCBs and diuretics." (PMID 40919025, 2025).